IDH1 (isocitrate dehydrogenase (NADP(+)) 1)
Diseases named in the same sentence as IDH1 in open-access papers (continued):
Sharing a sentence is not in itself a finding about the gene and the disease.
glioblastoma (continued). "We examined whether the histopathological findings from the original diagnostic tissue correlated with OS amongst patients with IDH1 negative glioblastoma." (PMID 28481241, 2017). "In children, low expression of IDH1 may be present in secondary glioblastomas." (PMID 28347331, 2017). "However, IDH1, a biomarker of secondary glioblastoma, showed low expression in our case." (PMID 28347331, 2017). "In combination with loss of nuclear ATRX expression, IDH1, 1p/19q and TERT promoter mutations define the most frequent type of infiltrative astrocytoma, while mutations in the EGFR gene (seen in 35 % of all cases of glioblastoma) are associated with primary glioblastoma." (PMID 26839018, 2016). "Although the IDH1 mutation was detected in CSF EVs of glioblastoma patients, it could not be detected in serum EVs of the same patients." (PMID 25720744, 2015). "The cohort included a total of 94 diffuse gliomas: 17 Grade II–III IDH1 wild type (IDH1wt), 28 Grade II–III IDH1 mutant (IDH1mut), 25 Grade IV (glioblastoma, GBM) IDH1wt, and 24 Grade IV IDH1mut." (PMID 26091668, 2015). "A recent study by Labussiere and colleagues also demonstrated that combined analysis of TERTp, EGFR and IDH1/2 defined distinct prognostic classes in glioblastomas, with the absence of both EGFR amplification and TERTp mutation associating with longer survival in patients with glioblastomas." (PMID 26369702, 2015). "Furthermore, interest in human IDH1 and IDH2 in tumor metabolism studies has recently increased since the publication of a cancer genome project showing that the genes encoding IDH1and IDH2 were mutated in glioblastoma multiforme (GBM), in 2008." (PMID 25502799, 2014). "IDH1 mutation itself may not be sufficient to account for a general HIF-1α-driven hypoxia in glioblastoma, as elevated HIF-1α levels are usually confined to severely hypoxic areas of necrosis such as palisades." (PMID 23451042, 2013). "To date, no prognostic microRNAs (miRNAs) for isocitrate dehydrogenase 1 (IDH1) wild-type glioblastoma multiformes (GBM) have been reported." (PMID 23988086, 2013). "Genome-wide mutational analyses have revealed somatic mutations in the cytosolic NADP+-dependent isocitrate dehydrogenase 1 (IDH1) in 12% of glioblastoma multiforme (GBM) patients." (PMID 22885298, 2012). "Notably, mutations in IDH1/2 and 1p/19q co‐deletion define distinct glioma subtypes, which exhibit better outcomes than IDH‐wildtype astrocytoma, also known as glioblastoma (GBM)." (PMID 41354084, 2025). "In the CNPI, this means editing genes such as SCN1A, DEPDC5, or KCNQ2 in focal epilepsy, or IDH1, TERT, or PTEN in glioblastoma, while also ensuring specificity and limiting collateral damage to the patient." (PMID 40806492, 2025). "Materials and Methods: We used isogenic glioblastoma cell lines that express IDH1 wild-type or, based on a TET-inducible system, the IDH1 mutant (mt) protein, and treated them with increasing doses of artesunate." (PMID 40564198, 2025). "To avoid this long-term effect, we expressed IDH1wt, mutant IDH1 R132H (IDH1mt), and vector control in LN319 glioblastoma cells in a TET-inducible system." (PMID 40564198, 2025). "Knockdown of IDH1 depletes NADPH levels and sensitizes glioblastoma cells to radiation, leading to cellular senescence." (PMID 41008904, 2025). "Histopathology confirmed glioblastoma IDH-wildtype CNS WHO grade 4 with immunohistochemistry, showing glial fibrillary acidic protein marker and ATRX positivity but IDH-1 R132H negativity." (PMID 40282523, 2025). "The epigenetic landscape of glioblastoma is impacted not only by MGMT, but also IDH1 and IDH2 status." (PMID 38672566, 2024).
glioblastoma (continued). "While patients with WHO grade II and III are younger (45 years), those with WHO grade IV tumors tend to be older (IDH1/2 wt astrocytoma with molecular features of a WHO grade IV tumor: 58 years; IDH1/2 wt glioblastomas: 55 years)." (PMID 38326661, 2024). "Glioblastoma (GBM) brain tumors lacking IDH1 mutations (IDHwt) have the worst prognosis of all brain neoplasms." (PMID 38326875, 2024). "These glioblastoma subtypes are either distinguished by the expression levels of EGFR, NF1, and PDGFRA/IDH1 or characterized by the status of overall chromatin accessibility, giving them varied sensitivities to drug treatment." (PMID 38760427, 2024). "The estimated overall survival for glioblastoma is 14.6 months overall —1.1 years for IDH-1 wild type and 3.6 years for IDH-1 mutant subgroups, presently classified as grade 4 astrocytomas." (PMID 36831580, 2023). "We found two genes, PSMC1P10 and AL132708.1, specific to patients with IDH1-wt and MGMT-methylated glioblastoma." (PMID 37568598, 2023). "In our study, we evaluated a large sample of 591 histologically diagnosed glioblastoma patients with homogenous clinical and molecular characteristics (ECOG PS 0–2, IDH1-2 wild-type treated with standard chemoradiotherapy)." (PMID 35626029, 2022). "The expression of wild-type IDH1 is upregulated in 65% of primary glioblastomas (GBM)." (PMID 36497259, 2022). "Nevertheless, IDH1 is overexpressed in glioblastoma (GBM), which could impact upon cellular metabolism and epigenetic reprogramming." (PMID 35877430, 2022). "There were two pilocytic astrocytomas, eight astrocytomas with IDH1-mutant, 15 astrocytomas with IDH1-wildtype, three oligodendrogliomas, NOS, 12 glioblastomas with IDH1-wildtype, and one ganglioglioma." (PMID 35204029, 2022). "A study reported that the molecular classification of glioblastoma involving IDH1, PDGFRA, EGFR, and NF1 substantially benefits the prediction of prognosis and response to therapy in glioblastoma patients." (PMID 36090889, 2022). "The number of distinct laboratory tests performed on glioblastoma patients operated at BWH was estimated to be 4.7-fold higher compared to patients from UMCU after correcting for age, sex, IDH1 status, postoperative KPS score, length of stay, and survival." (PMID 34997355, 2022). "Expression of PDGFRA, a glioblastoma (GBM)‐associated gene, was observed to be lower in comparisons of both CIC‐KO to CIC‐WT cells and IDH1‐R132H to IDH1‐WT cells, indicating that both CIC loss and the expression of IDH1‐R132H independently resulted in reduced expression of PDGFRA." (PMID 34767259, 2022). "Recently, some studies have shown that wild-type IDH1 is highly expressed in non-small cell lung carcinoma (NSCLC), primary glioblastomas (GBM), and several hematological malignancies and is correlated with disease progression." (PMID 35743098, 2022). "The strong cytotoxicity of Cyn was also confirmed on IDH1 mutant U-87 MG cells and patient-derived IDH wild-type glioblastoma cell lines NULU and ZAR." (PMID 35884887, 2022). "The significant difference in prognosis between IDH1 wild-type and IDH1 mutant glioblastoma multiforme (GBM) may be attributed to their metabolic discrepancies." (PMID 36389748, 2022).
glioblastoma (continued). "The R132H mutant of tumor-derived IDH1 showed decreased catalytic activity due to impaired isocitrate binding and reduced α-KG levels, leading to elevated HIF-1α protein levels in human glioblastoma cells." (PMID 34050894, 2022). "Glioblastoma (GBM) was diagnosed in 13 (including two recurrences), with nine MGMT methylated and two isocitrate dehydrogenase-1 (IDH-1) mutant." (PMID 36143263, 2022). "In the subgroup of glioblastomas, wildtype tumors (n = 35) showed higher values of TBF (p = 0.027) and nTBF (p = 0.022) than IDH1-mutant ones (n = 6)." (PMID 35741254, 2022). "MYC for cervical cancer, IDH1 for hepatic cirrhosis, MGMT for glioblastoma and CCND1 for anaplastic thyroid cancer were identified as genes with prognostic importance using survival analysis." (PMID 35001007, 2022). "Fifteen (93.8%) patients' tumors were diagnosed as glioblastoma (GBM) on histopathology (one patient had anaplastic astrocytoma), 13 (86.7%) were IDH1 wild-type and 2 (13.3%) were IDH1 mutants." (PMID 33767664, 2021). "Currently, the biomarkers for glioblastoma are mostly molecular and include EGFRvIII, ATRX, PTEN, IDH1, MGMT, and others." (PMID 34462698, 2021). "In Group B, elderly patients with IDH1 wild-type and MGMT methylated AA or glioblastoma will receive zotiraciclib and TMZ." (PMID 34207158, 2021). "The overall prognosis of some WHO II or III IDH1 wild-type astrocytoma patients is poor, and the survival time is equivalent to or slightly longer than that for IDH wild-type glioblastoma patients." (PMID 34458259, 2021). "We also observed an exclusion between IDH1 and EGFR, IDH1 and PTEN, along with a co-occurrence between EGFR and PTEN, which often appeared in glioblastoma." (PMID 34307451, 2021). "At the molecular level, 90% of glioblastomas harbor wildtype isocitrate dehydrogenase 1 and 2 genes (IDH1 and IDH2) distinguishing them from the remaining 10%, the so-called secondary glioblastomas, with a better prognosis." (PMID 33435218, 2021). "Mutations of anabolic signaling proteins phosphoinositide 3-kinase (PI3K), epidermal growth factor receptor (EGFR), and isocitrate dehydrogenase types 1 and 2 (IDH1, IDH2) have been widely detected in glioblastoma patient biopsy samples." (PMID 34769339, 2021). "NCT03224104 includes three experimental arms: In Group A, elderly patients with IDH1 wild-type and MGMT unmethylated AA or glioblastoma will receive zotiraciclib and radiation therapy." (PMID 34207158, 2021). "Promoter meythlation of the O6-methylguanine-DNA methyltransferase (MGMT) and IDH1/IDH2 has a particularly high prevalence in LGG, and methylation of the MGMT promoter is predictive for treatment response in glioblastoma patients." (PMID 34277415, 2021). "For example, in glioblastoma (GBM), the metabolic enzymes isocitrate dehydrogenase 1 (IDH1) and pyruvate kinase M2 (PKM2) were proposed as the link between tumor metabolism and epigenetics." (PMID 32331482, 2020). "Knockdown of IDH1 significantly reduces NADPH content, leading to reduction in GSH levels and induction of ROS in glioblastoma cells." (PMID 32408513, 2020). "To demonstrate application of the method for untargeted metabolomics we analysed IDH1 mutant and IDH1 wild-type LN18 glioblastoma cells." (PMID 32433536, 2020). "We also observed a consistent trend with the glioblastoma cohort, namely, a low level of ALDOC expression in the unmethylated MGMT and IDH1 wild-type group (p < 0.0001, p < 0.0001, respectively)." (PMID 31450822, 2019). "Wildtype IDH1 is reported as the major generator of cytosolic NADPH in glia cells and glioblastoma, while IDH1R132H consumes NADPH." (PMID 31888244, 2019).
glioblastoma (continued). "We selected the well‐validated IDH1‐wildtype, non‐CpG island methylated G26 GSC line as a target for our lentiviral transduction work to best recapitulate a primary glioblastoma GSC subpopulation." (PMID 30565681, 2019). "Overexpression of IDH1 R132H in human embryonic kidney cells 293 (HEK293T) and human primary glioblastoma cell line (U87MG) elevated HIF-1α levels." (PMID 29342092, 2018). "Additionally, we revealed that the overexpression of the DNA demethylase Ten-eleven translocation 2 (TET2) in IDH1-plasmid transfected glioblastoma multiforme (GBM) cells restored G0S2 expression." (PMID 30388142, 2018). "As described in the Section “The Role of Nrf2 in Cancer and Glioblastoma,” Nrf2 influences the transcription of ARE-containing genes to increase the levels of antioxidants and 2-HG (in IDH1 mutants)." (PMID 28424758, 2017). "Co-evaluation of BRAF, IDH1 and H3F3A-K27M status stratified young adult glioblastomas into four prognostic groups across the cohort (p < 0.00001)." (PMID 26452024, 2016). "Among the molecular biomarkers evaluated, BRAF, H3F3A-K27M, IDH1 and PDGFRA demonstrated prognostic relevance in young adult glioblastomas." (PMID 26452024, 2016). "Interestingly, the DEG from the high grade phenotype share a common genetic signature with a proneural type of glioblastoma (Gene set: VERHAAK_GLIOBLASTOMA_PRONEURAL), which is distinguished from other glioblastomas by lower age, better prognosis, PDGFRA expression, and frequent IDH1 mutation." (PMID 26524630, 2015). "These heterozygous point mutations occur commonly at arginine residues, at codon 132 of IDH1 and at codon 172 of IDH2, and are definitive markers of secondary glioblastoma and a significantly improved prognosis." (PMID 25785247, 2015). "We sought to confirm this impression by analyzing vessels in glioblastoma previously examined using chromogenic in situ hybridization (CISH) for EGFR and immunohistochemistry for mutant IDH1." (PMID 22298889, 2012). "Histological examination revealed a morphology consistent with either glioblastoma or anaplastic PXA: the tumor displayed high-grade features, harbored a BRAF V600E mutation, and was negative for IDH1 (R132H)." (PMID 41596318, 2026). "Considering glioblastoma is specifically defined as having wild-type IDH1, the upregulation of IDH1 but not IDH2 in this study is likely due to increased mutant IDH2 expression over wild-type IDH2 normally seen in the presence of wild-type IDH1." (PMID 41034696, 2025). "Glioblastoma (GBM) is the most aggressive form of adult-type diffuse glioma and is characterized by the absence of IDH1 and IDH2 mutations." (PMID 40016450, 2025).
glioblastoma (continued). "For the >55-year age group, all 11 cases were IDH1 negative, indicating they were classified as glioblastoma, IDH1-wildtype." (PMID 39165459, 2024). "The expression of LINC00324 in glioblastoma was significantly higher than that in other pathological types, as well as in IDH1-WT and 1p19q non-codel groups." (PMID 38530810, 2024). "In a recent study, conditioned media collected from the IDH1-wt (but not IDH1-mt) human glioblastoma cell line led to the reactivity of mouse primary astrocytes and high 11C-acetate uptake." (PMID 38932755, 2024). "All samples had molecular features of glioblastoma, including TERT promoter mutation (C228T), lack of IDH1 R132H mutation (confirmed by immunohistochemistry in all cases, and additionally by sequencing in two cases), and gain of chromosome 7." (PMID 38650010, 2024). "Common prognostic indicators of glioblastoma include Karnofsky performance status (KPS), age, extent of tumor resection, radiotherapy, chemotherapy, tumor size, tumor location, and molecular profiling for biomarkers such as IDH1, EGFR, PTEN, and MGMT." (PMID 37899778, 2023). "Despite being the most common malignant brain tumors in adults, IDH1-wildtype glioblastoma and IDH1-mutant astrocytoma are not sufficiently studied ultrastructurally." (PMID 38168422, 2023). "In clinical trials, glioblastoma patients with IDH1 R132H treated with vandetanib or ivosidenib in combination with temozolomide showed a significant increase in overall survival (OS) compared to glioblastoma patients without IDH1 R132H." (PMID 35888045, 2022). "Among 50 glioblastoma samples, only 6 were detected mutant for isocitrate dehydrogenase 1 (IDH1), p.R132H and none for isocitrate dehydrogenase 2 (IDH2) and histone H3-3A." (PMID 35303162, 2022). "Half of the patients with mutant glioblastomas in this study received prior treatment, which could have affected the results of the measurements, e.g., reducing TBF rates, predominantly in the IDH1-mutant glioblastoma group." (PMID 35741254, 2022). "Concurrent mutations in IDH1 and ATRX have been described previously in glioblastoma and appear more prevalent in tumours without receptor tyrosine kinase (RTK) activation." (PMID 35324914, 2022). "Of note, correlations of ADO gene expression and hypotaurine metabolite levels did not correlate in IDH1-WT glioblastoma." (PMID 34941573, 2022). "Pathology includes glioblastoma (3/3), methylguanine-DNA methyltransferase (MGMT) methylated (2/3), isocitrate dehydrogenase 1 (IDH1) mutant (0/3), epidermal growth factor receptor (EGFR) amplification (0/3), and α thalassemia/mental retardation syndrome X‐linked (ATRX) (3/3)." (PMID 36148206, 2022). "The RIGs included glioblastoma with IDH 1/2 wild-type (n = 7), glioblastoma not otherwise specified (n = 2), anaplastic astrocytoma with IDH1/2 wild-type (n = 1), and anaplastic astrocytoma not otherwise specified (n = 1)." (PMID 35505351, 2022). "Seven studies compared the characteristics of patients with cystic versus non-cystic glioblastoma, specifically sex, age, median pre-operative KPS, mean tumor size on pre-operative imaging and molecular markers (IDH1 mutation and pMGMT methylation status)." (PMID 36605383, 2022).